ASIC2 (acid sensing ion channel subunit 2)
Diseases named in the same sentence as ASIC2 in open-access papers (continued):
Sharing a sentence is not in itself a finding about the gene and the disease.
lung adenocarcinoma (1 paper, 2022). A carcinoma that arises from the lung and is characterized by the presence of malignant glandular epithelial cells. "Bioinformatic analysis of the gene expression in the tissues from the patients with lung adenocarcinoma revealed possible implications of ASIC1, ASIC2, ASIC3, ASIC4, α-ENaC, and γ-ENaC in the disease progression." (PMID 35837090, 2022).
major depressive disorder (1 paper, 2023). An episode of depression lasting two or more weeks without an intervening episode of mania. "In humans, ASIC2 gene polymorphisms have been implicated in psychiatric illnesses, including major depressive disorder and panic disorder." (PMID 36793786, 2023).
migraines (1 paper, 2022). "For the incessant problem of migraines, drugs targeting ASIC2 subunits in ASIC1a/2a heterotrimers may well reduce the pain experienced by patients." (PMID 35207035, 2022). "In migraines, meningeal pH is reduced, which provides a reasonable hypothesis for the mechanism behind ASIC2 subunits being involved in pain processing." (PMID 35207035, 2022). "Future studies may investigate this in an ASIC2 KO mouse migraine model to see whether it is involved." (PMID 35207035, 2022). "In summary, there is no direct evidence to support ASIC2 responsible for migraines." (PMID 35207035, 2022).
osteoporosis (1 paper, 2019). A condition of reduced bone mass, with decreased cortical thickness and a decrease in the number and size of the trabeculae of cancellous bone (but normal chemical composition), resulting in increased fracture incidence. "Finally, further studies with an animal model of osteoporosis need to be conducted to analyze the change in ASIC2 expression in the administration of antiresorptive drugs to treat osteoporosis." (PMID 31531354, 2019). "ASIC2 may be crucial in the pathogenesis of osteoporosis and could serve as a therapeutic target for antiosteoporotic therapies." (PMID 31531354, 2019). "ASIC2 could be crucial in the pathogenesis of osteoporosis and could serve as a therapeutic target for antiosteoporotic therapies." (PMID 31531354, 2019). "Therefore, the clinical relevance of the findings from these in vivo studies indicates that ASIC2 may be crucial in osteoclast bone resorption in the pathophysiology of osteoporosis." (PMID 31531354, 2019).
pulmonary fibrosis (1 paper, 2021). Chronic progressive interstitial lung disorder characterized by the replacement of the lung tissue by connective tissue, leading to progressive dyspnea, respiratory failure, or right heart failure. "Among the 861 differentially downregulated genes, PTE inhibited pulmonary fibrosis by downregulating ASIC2." (PMID 34321072, 2021). "Moreover, we found that ASIC2 as a downstream effector of PTE may be involved in the activity of PTE to alleviate pulmonary fibrosis." (PMID 34321072, 2021). "Compared with the TGF-β1 + PTE group, the transfection of ASIC2 overexpression plasmid stimulated the EMT and ECM accumulation and inhibited apoptosis and autophagy, suggesting that PTE inhibited pulmonary fibrosis by downregulating ASIC2." (PMID 34321072, 2021).
scoliosis (1 paper, 2024). A congenital or acquired spinal deformity characterized by lateral curvature of the spine. "For that, we compared spinal alignment between control and Asic2 KO mice by using CT to determine the level of scoliosis and kyphosis in these mice." (PMID 36951012, 2024). "The results showed that 30% (5 or 17) of the Asic2 KO mice exhibited mild scoliosis, measured as a Cobb angle ranging from 10 to 15°." (PMID 36951012, 2024). "Interestingly, we found that Asic2 ablation affects only the lateral curve of the spine, causing scoliosis, without causing kyphosis or affecting hip joint morphology." (PMID 36951012, 2024).
Stroke (1 paper, 2023). Sudden impairment of blood flow to a part of the brain due to occlusion or rupture of an artery to the brain. "In those with focal brain ischemia due to a stroke, the deletion of ASIC2 channels has a protective effect on hippocampal, cortical, and striatal neurons by decreasing the effects of acidosis-induced injury." (PMID 36830598, 2023).
tumor (12 papers, 2008 to 2026). "Chi-square test showed that ASIC2 expression was associated with recurrence status, tumor stage, distant metastasis and NFAT1 positivity." (PMID 28927426, 2017). "The acid-sensing ion channels ASIC1 and ASIC2, as well as the transient receptor potential vanilloid channels TRPV1 and TRPV4, are proton-gated cation channels that can be activated by low extracellular pH (pHe), which is a hallmark of the tumor microenvironment in solid tumors." (PMID 34199609, 2021). "The majority of cancer research has been on ASIC1, whereas the roles of ASIC2 and ASIC3 have been explored in only a limited number of studies, but they seem related to acidification of the tumor microenvironment." (PMID 41516419, 2026). "According to them, ASIC1 and ASIC2 are co-expressed in normal cells, and the lack of ASIC2 in tumor cells leads to a large inward cation current." (PMID 34199609, 2021). "Additional amplification of WT1, ERC1, ASIC2 and MTCP1 and deletion of CDKN2A and MLLT3 were found in recurring MFS (case 8b) but not in the original tumor (case 8a)." (PMID 38791144, 2024). "The authors found that ASIC2 is not expressed in the plasma membrane of glial cells, whereas ASIC1 is indeed expressed on these tumor cells, analogous to our findings in BCC." (PMID 34199609, 2021). "In contrast to these tumor entities, BCCs were negative in ~50% of the samples, which is a striking immunohistochemical feature and similar to the results we found for GPR31, GPR151, TASK1, TASK3 and ASIC2." (PMID 36674553, 2023).
cancer (7 papers, 2015 to 2026). A tumor composed of atypical neoplastic, often pleomorphic cells that invade other tissues. "In particular, TRPV6, ASIC2, MMP13, and FOXH1 are well known to be implicated in cancer development." (PMID 38457049, 2024). "Stronger staining of ASIC2 was observed in cancer cells than in adjacent normal tissue." (PMID 28927426, 2017).
neurodegenerative disease (2 papers, 2017 to 2022). A disorder of the central nervous system characterized by gradual and progressive loss of neural tissue and neurologic function. "However, in the light of some contradictory evidence and no distinct data specifying the ASIC2 contribution, there is a need to further investigate the unique role of these channels in these neurodegenerative diseases." (PMID 35207035, 2022).
infection (1 paper, 2016). The state of being infected such as from the introduction of a foreign agent such as serum, vaccine, antigenic substance or organism. "To examine syntabulin’s regulatory effect on ASIC2 in neurons, we used lentiviral infection to knockdown endogenous syntabulin expression and then checked ASIC2 levels." (PMID 26868290, 2016).
inflammation (1 paper, 2024). Aberrant reaction of the microcirculation characterized by movement of fluid and leukocytes from the blood into extravascular tissues. "The importance of ASIC2 in hepatic cell activation has not been addressed and may represent a potential mechanism contributing to HFD-induced liver inflammation." (PMID 39224121, 2024).
neurological disease (1 paper, 2019). "ASIC2 expression was quantified in human brain tissues of 62 cases with secondary progressive MS and 32 controls (affected by other non‐neurological disease)." (PMID 30549327, 2019).
renal diseases (1 paper, 2021). "Finally, the presence of ASIC2 mRNA was also detected in kidney biopsies from patients with INS but not in any of the patients with other renal diseases." (PMID 34166227, 2021).
ASIC2 also shares sentences with these, for which no sentence is quoted: temporal lobe epilepsy (3 papers); Cerebral ischemia (2); experimental autoimmune encephalomyelitis (2); Obesity (2); preeclampsia (2); Seizure (2); status epilepticus (2); Acidosis (1); adenoid cystic carcinoma (1); amyotrophic lateral sclerosis (1); autism spectrum disorder (1); autoimmune disease (1); basal cell carcinoma (1); brain tumor (1); cerebrovascular diseases (1); gastrointestinal disorders (1); heart failure (1); Hyperreflexia (1); Insulin resistance (1); interstitial cystitis (1); irritable bowel syndrome (1); ischemia (1); leukaemia (1); malaria (1); malignant glioma (1); mental disorder (1); metastatic melanoma (1); minimal change disease (1); pancreatic cancer (1); panic disorder (1).
A further 7 diseases each share a sentence with ASIC2 in 1 paper.